OR14K1 (olfactory receptor family 14 subfamily K member 1)
Description:
Odorant receptor.
Synonyms: OR5AY1; OR1-39; OR1.5.9
Tractability: Antibody: UniProt places it where antibodies can reach, with medium confidence; UniProt predicts a signal peptide or a membrane-spanning region; its Gene Ontology location is reachable by antibodies, with medium confidence.
Gene: Protein-coding gene on chromosome 1 (247,738,615 to 247,739,559, forward strand). Ensembl gene ENSG00000153230.
Subcellular location: Cell membrane
Pathways (Reactome):
Sensory Perception: Expression and translocation of olfactory receptors
Gene Ontology:
Molecular function: odorant binding; olfactory receptor activity; G protein-coupled receptor activity
Biological process: sensory perception of smell; detection of chemical stimulus involved in sensory perception of smell; G protein-coupled receptor signaling pathway
Cellular component: plasma membrane; membrane
Homologues: Orthologues: chimpanzee OR14K1 (97% identical), macaque OR14K1 (94% identical), pig OR14K1 (71% identical). Paralogues in human: OR14A16 (49% identical), OR14A2 (49% identical), OR14J1 (48% identical), OR14L1 (47% identical), OR14I1 (45% identical), OR14C36 (42% identical), OR5AP2 (40% identical), OR5AS1 (40% identical), OR8K3 (40% identical), OR5A1 (39% identical), OR9K2 (39% identical), OR8U1 (39% identical), and 84 more.